E2F1 (E2F transcription factor 1)
Diseases named in the same sentence as E2F1 in open-access papers (continued):
Sharing a sentence is not in itself a finding about the gene and the disease.
glioma (continued). "In contrast, miR-106a-5p inhibits cell proliferation and induces apoptosis by targeting E2F1 (E2F transcription factor 1) in gliomas." (PMID 24013584, 2013). "Our results showed that the expression of E2F1 was regulated by miR-329 and the level of E2F1 protein expression was inversely correlated with miR-329 expression in glioma cells." (PMID 23866847, 2013). "E2F1 was identified as a significant target of miR-329 by luciferase assays, miR-329 was able to induce the G1/S arrest and inhibit proliferation of glioma cells through E2F1-mediated suppression of Akt pathway." (PMID 23866847, 2013). "Among these crucial signaling networks, the Akt pathway and E2F1 have emerged as being particularly important in glioma pathogenesis, which is correlated with poor prognosis in multiple glioma subtypes." (PMID 23866847, 2013). "Recently, miR-106a-5p was found through bioinformatics prediction followed by experimental validation to inhibit glioma cell growth by targeting the transcription factor E2F1." (PMID 24013584, 2013). "We also showed that miR-329 inhibits proliferation through E2F1-mediated suppression of Akt phosphorylation in glioma cells." (PMID 23866847, 2013). "In good correlation with our data, lower expression of E2F1, a target of miR-20a and cyclin D1, a target of both miR-20a and miR-17 was found to predict longer survival in gliomas." (PMID 21483847, 2011). "We employed the rat glioma cell line, C6, as an in vitro cancer model, and showed that the shE2f1 (short hairpin RNA against E2f1 mRNA) is a potent tool for impeding cell proliferation, since it diminished C6 proliferation 3.5 to 4-fold." (PMID 21637599, 2010). "In this study, the introduction of specific short hairpin RNAs (shRNAs) reduced E2f1 expression by up to 77%, and impaired rat glioma cell proliferation by approximately 70%, as compared to control cells." (PMID 21637599, 2010). "RAD51AP1 is a necessary mediator of E2F1 for glioma chemoresistance." (PMID 37283490, 2023). "CDCA8, in combination with E2F1, accelerates glioma proliferation and migration." (PMID 36855818, 2023). "We then analyzed the role of E2F1 in TMZ-induced glioma cell apoptosis." (PMID 37283490, 2023). "AQP1 may be implicated in glioma formation by interacting with the transcriptional regulation networks involving the FOXO4, MAZ, and E2F1/2." (PMID 38057925, 2023). "The authors identified E2F1 as a direct functional target of miR-106a, suggesting that the effect of miR-106a on the glioma suppressive effect may result from the inhibition of E2F1 via posttranscriptional regulation." (PMID 37627777, 2023). "Whether this indicates that E2F1 is important for glioma stem cells (GSC) residing within tumors or whether this is because stem cell populations are artificially driven by exogenous growth factors in the GS culture system is unknown." (PMID 36213002, 2022). "Moreover, the StarBase database indicated that E2F1 expression was in positive correlation with SNHG18 expression in glioma tissues." (PMID 34937497, 2022). "MiR-205 confers cisplatin resistance in glioma cells by up-regulating the expression level of E2F1." (PMID 35674307, 2022). "Furthermore, mEHT treatment triggers the up-regulation of the E2F1 protein, which is involved in E2F1-mediated apoptosis in various glioma cell lines." (PMID 35681533, 2022). "Herein, we describe a selection of oncogenic (GLI-1/2/3, E2F1–8, STAT3, and HIF-1/2) and tumor suppressor (NFI-A/B, TBXT, MYT1, and MYT1L) TFs that are deregulated in gliomas and are subsequently associated with tumor development, progression, and migratory potential." (PMID 35409080, 2022). "We hypothesized that SNHG18 could facilitate the progression of glioma, and we demonstrated that SNHG18 could regulate the malignant biological behaviors of glioma cells and E2F1 bound to the SNHG18 promoter region to promote SNHG18 transcription." (PMID 34937497, 2022).
glioma (continued). "In glioma patients, high STAT3 signaling is associated with high E2F1 and H2AZ2 expression." (PMID 35058574, 2022). "It acts downstream of E2F1 in osteosarcoma, glioma, and retinoblastoma." (PMID 36012581, 2022). "In addition, miR-205 directly targets E2F transcription factor 1 (E2F1) to downregulate its expression in cisplatin-sensitive glioma cell lines." (PMID 35674307, 2022). "We searched for transcription factors that are positively co-expressed with EIF4EBP1 in gliomas and found EIF4EBP1 mRNA expression to be significantly and positively associated with the mRNA expression levels of MYBL2, FOXM1, ETS1, HIF-1A, JUN, E2F1, and E2F6 in the REMBRANDT dataset." (PMID 35228525, 2022). "We detected the expression of E2F1 in glioma tissues and GSCs." (PMID 35371308, 2022). "In conclusion, FGF14-AS2 could accelerate tumorigenesis of glioma by forming a feedback loop with the miR-320a/E2F1 axis which suggested that FGF14-AS2 could serve as a therapeutic target for glioma." (PMID 34659533, 2021). "Functional assays further disclosed that E2F1 acts as an oncogene in glioma." (PMID 34659533, 2021). "Given E2F1 as oncogene in glioma and our microarray analysis, we deduced that E2F1 may mediate the effect of CDCA8 in glioma." (PMID 33542211, 2021). "Abnormal overexpression of E2F1 has also been reported in glioma." (PMID 34079762, 2021). "Our results suggested that Pontin bound to E2F1 relying on the presence of the ATPase domain, which contributed majorly for the following transcription response amplification and growth promotion of Pontin in glioma." (PMID 33542204, 2021). "Besides, the positive correlation between Pontin and six E2F1 targets (AURKA, CDK1, CDK4, CCNA2, CCNB2, E2F8) assessed by GEPIA in glioma further supported the positive regulation of E2F1 targets expressions by Pontin." (PMID 33542204, 2021). "The interaction between CDCA8 and E2F1 verified by co-IP assay showed that CDCA8 may regulate the progression of glioma through interacting and regulating E2F1." (PMID 33542211, 2021). "Here, this study reports that there might be an E2F1/miR‐107/CCND1 axis that mediates the malignant development of glioma cells in vitro and in vivo with the implication of Wnt/β‐catenin signaling." (PMID 34758200, 2021). "Moreover, E2F1 has been identified as the target molecule of miRNAs in the regulation of development or cisplatin resistance of glioma cells." (PMID 33542211, 2021). "In our study, we found that E2F1 was upregulated in glioma tissues and cells and could be directly suppressed by miR-320a." (PMID 34659533, 2021). "Previously, it has been reported that E2F1 expression could be regulated by UPS in glioma and liver cancer." (PMID 34564711, 2021). "As the potential downstream of CDCA8, knockdown of E2F1 could alleviate or reverse the glioma growth induced by CDCA8 overexpression." (PMID 33542211, 2021). "And we further screened target genes of CDCA8 and investigated the potential role of CDCA8 synergized with the transcription factor E2F1 in glioma cell proliferation and migration, indicating the underlying molecular mechanism of CDCA8/E2F1-associated tumor suppression in glioma treatment." (PMID 33542211, 2021). "Studies have also suggested that E2F1 may function as an oncogene in glioma 24-26; however, the exact role and mechanism of E2F1 in the lncRNA-miRNA network has not been determined." (PMID 34659533, 2021). "Taken together, the results of this study demonstrated that E2F1/FGF14-AS2/miR-320a formed a feedback loop to regulate the progression of glioma and suggested that FGF14-AS2 could serve as a biomarker for glioma." (PMID 34659533, 2021). "The ECT2/PSMD14/PTTG1 axis promoted glioma proliferation by stabilizing E2F1." (PMID 33381564, 2020).
glioma (continued). "PPARα inhibited growth of glioma cells through the E2F1/miR-19a feedback loop." (PMID 33381564, 2020). "MiR-205 regulates E2F1 expression to promote the cisplatin sensitivity of glioma cells." (PMID 32795273, 2020). "miRNA-320 and miRNA-329 inhibited glioma proliferation by targeting E2F1." (PMID 33381564, 2020). "Intracranial xenograft models further elucidated that BIP-MPC-NP enhanced TMZ chemosensitivity via attenuating the EGFR and MET signaling pathways, including phosphorylation of p38 and reducing E2F1 expression accompanied by elevated TTP in TMZ-resistant gliomas." (PMID 32001707, 2020). "Therefore, it is critical to explore a potential effective targeting therapeutic strategy simultaneously targeting EGFR and MET to overcome TMZ resistance via E2F1 in glioma." (PMID 32001707, 2020). "In addition, it is also found that FER1L4 can be used as competitive endogenous RNA (ceRNA) to adsorb E2F1 and thereby up‐regulate E2F1, thus promoting the cycle and proliferation of glioma cells." (PMID 30887657, 2019). "In addition, it is also found that FER1L4 can be used as competitive endogenous RNA to interact or bind with miR‐371 and thereby up‐regulate E2F1, thus promoting the cycle and proliferation of glioma cells." (PMID 30887657, 2019). "The expression of LncRNAs FER1L4 and E2F1 in gliomas at 47 different grades was detected using RT‐PCR and the results showed that the expression of FER1L4 in different grade WHO IV glioma tissues (27.32 ± 1.90) was dramatically higher than that in grade WHO III gliomas (14.24 ± 1.41) (P < 0.001)." (PMID 30887657, 2019). "In contrast, knockdown of E2F1 by RNA interference impairs proliferation of rat glioma cells." (PMID 29661169, 2018). "In view of this, we hypothesized that in glioma cells, E2F1 may be involved in the transcriptional regulation of c-myc by KPNA2." (PMID 30115078, 2018). "To test this hypothesis, we first examined the effects of KPNA2 exerting to E2F1 in the glioma cells." (PMID 30115078, 2018). "However, other studies, including the present study, have identified E2F1 oncogenic functions in gliomas." (PMID 27835866, 2016). "Thus, microarrays combined with Pearson correlation analysis revealed that the miR-17-92 cluster was positively correlated with E2F1 in glioma cells." (PMID 27835866, 2016). "si-E2F1 triggered the inhibition of glioma cell proliferation, invasion and aerobic glycolysis." (PMID 27835866, 2016). "Therefore, by restraining E2F1 transcription, miR-10b inhibition coordinately reduces the levels of many critical tumorigenic factors in glioma, some of which represent promising candidates for targeted molecular therapies." (PMID 25738367, 2015). "In humans, miR-329 may inhibit cell proliferation in human glioma cells by regulating E2F1-mediated suppression of the Akt pathway." (PMID 25853900, 2015). "Targeting to the miR-329/E2F1 interaction or rescuing miR-329-expression may be a new therapeutic application to treat glioma patients in the future." (PMID 23866847, 2013). "However, others have shown overexpression of E2F1 in gliomas triggered apoptosis and suppressed tumor growth in vitro and in vivo." (PMID 23866847, 2013). "E2F1 functions as an oncogene in gliomas, the oncogenic function of E2F1 may be mainly marked in glioma." (PMID 23866847, 2013). "MiR-329 may inhibit cell proliferation in human glioma cells through regulating E2F1-mediated suppression of Akt pathway." (PMID 23866847, 2013). "There is a significant correlation between high levels of E2F1 protein and high-grade glioma." (PMID 22761708, 2012). "Notably, E2F1 enhances cell proliferation by binding to promoter regions of genes essential for cell cycle regulation and DNA replication, creating an “addiction” to this multifaceted transcription factor in glioma prognosis." (PMID 41158756, 2026). "In glioma, E2F1 could be inhibited by miR-329 to down-regulated cell proliferation by Akt pathway." (PMID 35371308, 2022).
glioma (continued). "Thus, CDCA8/E2F1 axis is responsible for glioma cell growth and migration in vitro or in vivo." (PMID 33542211, 2021). "In addition, FGF14-AS2 was observed to promote glioma progression via the miR-320a/E2F1 axis." (PMID 34659533, 2021). "Therefore, we examined the expression of E2F1 in glioma tissues and normal brain tissues." (PMID 34758200, 2021). "Therefore, this study hypothesized that there might be an E2F1/miR‐107/CCND1 axis involved in the pathogenesis of glioma." (PMID 34758200, 2021). "Moreover, the results of co-IP assay indicated that CDCA8 and E2F1 may act as coregulators in glioma malignancy." (PMID 33542211, 2021). "Interestingly, a previous report showed that lncRNA DLX6‐AS1 could relieve E2F1 by sponging miR‐197‐5p and thus promote the glioma carcinogenesis." (PMID 32951317, 2020). "Similarly, E2F1 was significantly higher in grade WHO IV gliomas (32.01 ± 2.67) than in grade WHO III gliomas (18.57 ± 1.64) and grade WHO II (7.443 ± 1.64) (P < 0.001) and with the increase in the grade, its expression also showed a gradually increasing trend." (PMID 30887657, 2019). "Similarly, high expression of E2F1 predicts a poor prognosis of gliomas." (PMID 30887657, 2019). "Reports have shown that downregulation of miR-136-5p in human gliomas is significantly associated with a more aggressive and poor prognostic phenotype; conversely, its overexpression promotes apoptosis and modulates sensitivity to cisplatin by targeting AEG-1, Bcl-2, and E2F1." (PMID 29152149, 2017). "In addition CDK6 activates transcription factor E2F1/2 that might activate several drug-resistant genes which are up-regulated in glioma cells." (PMID 28467792, 2017). "Of note, although the proposed p21-dependent control of E2F1 activity by miR-10b was observed only in a subset of cultured glioma cell lines, specifically those expressing high levels of p21, this mechanism may be widely applicable, as the majority of GBM tumor samples express high levels of p21." (PMID 25738367, 2015). "In summary, our findings collectively demonstrate that ATAD2 promotes malignant progression in glioma and synergistically up-regulates PDK1 expression in cooperation with E2F1." (PMID 41158756, 2026). "In glioma, HOXA-AS2 affects the expression of E2F8, E2F1, ATF3, and STAT1, promoting the proliferation of glioma stem cells (GSCs) and enhancing their aggressiveness." (PMID 38311789, 2024). "We next wanted to investigate the transcription factor responsible for TSPYL2 upregulation upon genotoxic stress and we decided to investigate E2F1 involvement because of its role in the DDR and in glioma sexual dimorphism." (PMID 36918555, 2023). "We further demonstrated that RAD51AP1 is a mediator of E2F1 in TMZ resistance and that targeting RAD51AP1 has great potential in sensitizing glioma cells to TMZ." (PMID 37283490, 2023). "Western blot suggested enhanced expression of E2F1 in EGFRvIII-positive and TMZ-treated glioma cells." (PMID 37283490, 2023). "At the same time, there are reports that E2F1 can enhance the expression of PTTG1 in pituitary tumors, glioma, and adrenocortical carcinoma." (PMID 35210406, 2022). "Since E2Fs bind to similar DNA binding sequences, we conducted correlative analysis of H2AZ2 with E2F1 and E2F4 in TCGA glioma." (PMID 35058574, 2022). "The results demonstrated that the expression of c-Myc, cyclin D1, cyclin A, and E2F1 decreased after knocking down TFE3, suggesting that the TFE3-mediated overexpression of HOXD-AS2 promoted the cell cycle progression in glioma cells." (PMID 35269968, 2022). "miR‐107 was poorly expressed, whereas E2F1 and CCND1 were highly expressed in glioma tissues and cells." (PMID 34758200, 2021). "This study aims to explore the interaction between E2F transcription factor 1 (E2F1) and miR‐107 in the progression of glioma." (PMID 34758200, 2021).
glioma (continued). "Among the eight E2F family members, up-regulated E2F1 expression gene reportedly induced apoptosis in glioma cell lines, while E2F3 knockdown inhibited proliferation and migration in glioma." (PMID 34617871, 2021). "We detected TF binding sites for E2F1, HMX1, PAX5, REST and ZBTB6 in the promoters of DEGs present within the top six ‘glioma TADs’." (PMID 34341417, 2021). "This study suggested that E2F1 reduces miR‐107 transcription to induce CCND1 upregulation, which leads to progression of glioma via Wnt/β‐catenin signaling activation." (PMID 34758200, 2021). "This study confirmed the oncogenic roles of E2F1 and CCND1 and the anti‐tumorigenic role of miR‐107 in glioma." (PMID 34758200, 2021). "We found the set of transcription factors, including REST, E2F1 and NFKB1, that are most likely to regulate gene expression in multiple TADs, containing specific glioma-related genes." (PMID 34341417, 2021). "A similar study found that miR‐384 inhibited the malignant progression of glioma by inhibiting PIWIL4 expression by targeting its 3′‐UTR region, while miR‐331‐3p downregulated E2F1 expression and promoted the proliferation and migration of hepatoma cells." (PMID 32892482, 2020). "In glioma, however, FER1L4 promoted cancer progression via sponging miR-371 and upregulation of E2F1." (PMID 32140077, 2020). "When glioma cells were treated with BIP-MPC-NP, the E2F1 mRNA and protein expression levels were significantly downregulated." (PMID 32001707, 2020). "In the Glioma pathways (KEGG), 3 genes were down-regulated by both citalopram and escitalopram (E2F1, DAPK1, CCND1)." (PMID 28467792, 2017). "Compared with TERT, Survivin, Cox2 and E2F1 promoter, the transcriptional activity of FOS promoter was higher in glioma cell lines." (PMID 26571389, 2015). "Compared with the TERT, Survivin, Cox2 and E2F1 promoters, the transcriptional activity of the FOS promoter was higher in all three glioma cell lines.." (PMID 26571389, 2015). "We previously reported that EZH2 was upregulated in glioma and promoted glioma cells growth through inhibition of CDK4/6-pRb-E2F1 signal pathway." (PMID 25831237, 2015). "In this study, we compared the transcriptional activities of FOS, TERT, Survivin, E2F1, Cox2 and CMV promoter in human glioma lines." (PMID 26571389, 2015). "We evaluated the expression levels of E2F1 and PDK1 using 126 surgical glioma specimens." (PMID 41158756, 2026). "HOTAIR has been identified as a potential biomarker for glioma subtypes and tumor grades, with its silencing in glioblastoma cell lines (LN229 and U87) shown to disrupt cell cycle regulation by downregulating E2F1, cyclins, CDKs while upregulating inhibitors p16 and p21." (PMID 40004468, 2025). "In this study, we focused on Cell Cycle Protein Dependent Kinase Inhibitor 1A (CDKN1A), which is a regulator of the E2F1 transcription factor and may play a key role in DDR‐related signaling pathways in gliomas and influence TMZ resistance." (PMID 38600891, 2024). "Because E2F1 was regulated by TMZ and DP1 was minimally impacted by this treatment, we concluded that E2F1 has a key role in RAD51AP1 regulation, as least in TMZ-resistant glioma cells." (PMID 37283490, 2023). "Therefore, the E2F-1/MAD2L2/c-MYC axis facilitates the stemness and aggressive behaviors, such as proliferation and invasion, in glioma, providing new insights for the treatment of this disease." (PMID 38017538, 2023). "Additionally, we investigated the regulatory effects of E2F transcription factor 1 (E2F1) on SNHG18, to explain the mechanism of SNHG18 dysregulation in glioma." (PMID 34937497, 2022).